RUNX3 (RUNX family transcription factor 3)
Diseases named in the same sentence as RUNX3 in open-access papers (continued):
Sharing a sentence is not in itself a finding about the gene and the disease.
tumor (continued). "Moreover, hypoxia-inducible factor-1α (HIF-1α), a key transcription factor that induces angiogenesis and tumor aggressiveness is destabilized by RUNX3." (PMID 26375442, 2015). "In addition to stage III, early recurrence was associated with loss of RUNX3 and CDKN2A, both of which are known tumor suppressor genes in CRC and previously reported to be associated with clinical outcome in CRC." (PMID 25879218, 2015). "We believed that our findings provided the novel insight into the connection between AMPKα signaling and expression of RUNX3 affected by baicalein, and also highlighted the tumor suppressor role of AMPKα and RUNX3 that were involved in the anti-tumor effect of baicalein." (PMID 25948105, 2015). "Similarly, overexpression of Pim-1 was associated with advanced stage and tumor aggressiveness in ACC, along with low level of RUNX3." (PMID 26359351, 2015). "RUNX3 tumor suppressor function includes an anti-angiogenesis function." (PMID 26375442, 2015). "The identified RUNX3 methylation in HROC43 und HROC183 confirms an advanced tumor stage." (PMID 26618628, 2015). "Furthermore, we for the first time demonstrated a positive feedback regulation of ERK1/2 signaling by RUNX3, in turn, this would further enhance the anti-tumor efficacy of baicalein." (PMID 25948105, 2015). "Additionally, miR-106b was reported to induce epithelial-mesenchymal transition (EMT), which is essential for tumor metastasis, by suppressing RUNX3." (PMID 26053181, 2015). "For example, RUNX3 P1 hypomethylation is a feature of cytolytic CD8+ T lymphocytes and natural killer cells (NK), correlating with both the high RUNX3 mRNA expression of these two cell types and genetic requirement of RUNX3 for their intrinsic ‘tumor killing’ functions." (PMID 26682246, 2015). "As well, restoration of RUNX3 expression greatly suppresses tumour growth and metastasis." (PMID 24447545, 2014). "Strikingly, RUNX3 was demonstrated to inhibit tumor metastasis and angiogenesis in vivo." (PMID 24475196, 2014). "A possible role for RUNX3 as a tumor suppressor in ER+ BCs has been suggested." (PMID 24416132, 2014). "The study design was to monitor the epigenetic changes in two tumor suppressor genes, RUNX3 and PRSS8, and follow up with a screening for epigenetic changes in more tumor suppressor genes if CSE-induced changes were to be observed in the RUNX3 and PRSS8 marker genes." (PMID 23724145, 2013). "RUNX3 is a target of TGF-β-mediated tumor suppressor pathway." (PMID 23457532, 2013). "In addition to the invasion and migration changes brought out by RUNX3, it appears to exert its tumor suppressor activity through antiangiogenic." (PMID 23457532, 2013). "Furthermore, in tumor cell lines where Src was activated, tyrosine phosphorylated RUNX3 was mainly detected in the cytoplasm." (PMID 23585863, 2013). "Despite our work suggested that the role of RUNX3 as tumor suppressor might be played through the cell cycle related proteins and TIMP-1, more precise mechanism remained to be elucidated deeply." (PMID 22457727, 2012). "It was reported previously that nicotinamide could epigenetically stabilize RUNX3, one of the important tumor suppressors." (PMID 22028816, 2011). "Previous studies strongly suggested that Runx3 is a tumor suppressor in various carcinomas, including gastric and breast carcinoma and its loss is related to frequently inactivation by dual mechanism of protein cytoplasmic mislocalization and promoter hypermethylation." (PMID 24250365, 2011). "Interestingly, some of these genes have been previously associated with CIMP in other tumor types, such as p73, GSTP1, SOCS-1, CACNA1G, CRABP1, NEUROG1 and RUNX3." (PMID 20830311, 2010). "These, and similar reports, established that RUNX3 appears to function as a tumor suppressor." (PMID 21203558, 2010). "As the TGF-β signalling pathway plays an important role in the growth control of human colonic epithelial cells, RUNX3 may also act as a tumour suppressor gene in this tissue." (PMID 19223906, 2009).
tumor (continued). "Taken together, RUNX3 acts as a tumor suppressor in various cancers." (PMID 19521519, 2009). "For example, Runx3 was described as a tumour suppressor in gastric carcinogenesis." (PMID 19190631, 2009). "RUNX3 is believed to have tumour suppressor properties in several cancer types." (PMID 19223906, 2009). "As might be expected, if RUNX3 were behaving as a tumour suppressor, the decreased expression of this protein in gastric, lung and oesophageal cancers has been associated with worse patient outcome." (PMID 19223906, 2009). "RUNX3 methylation was found in all the three stages of these tumours." (PMID 15574200, 2004). "Thus, RUNX3 broadly influences immune signal output through transcriptional regulatory pathways, potentially playing a central role in maintaining tumor–myeloid cell interactions and providing potential intervention strategies for targeting the RUNX3–MP interaction axis." (PMID 40916017, 2025). "Resveratrol was observed to significantly reduce this hypermethylation of the RUNX3 promoter, resulting in an increase in RUNX3 protein expression, thereby restoring RUNX3 protein expression both in vitro and in xenograft models, highlighting its role in reactivating tumor suppressor genes." (PMID 41463545, 2025). "Thus, RUNX3 may be a bona fide tumor suppressor in FL and be inactivated by several mechanisms, including 1p36 deletions and/or disruptive ARID1A mutations." (PMID 39843653, 2025). "In GBM, LMTK2 mediates tumor suppression by upregulating RUNX3, which in turn inhibits the Notch signaling pathway; low levels of LMTK2 are associated with poor overall survival, thereby suggesting that both LMTK2 and RUNX3 collectively influence the prognosis of GBM patients." (PMID 38430423, 2024). "In summary, RUNX3 could act as a major regulator of tumor progression and metastasis." (PMID 38172737, 2024). "Notably, we observed differences in RUNX3 isoform usage; the longer isoform, p46, may act as a tumor suppressor in BOS while a shorter RUNX3 isoform predominates in AML." (PMID 39614348, 2024). "However, since IO/TKI therapy has just recently emerged, whether RUNX3 could regulate anti-tumor immunity, and the correlation between RUNX3 and IO/TKI benefits, has not been clarified yet." (PMID 38172737, 2024). "However, whether RUNX3 could regulate anti-tumor immunity, and the correlation between RUNX3 and IO/TKI benefits, has not been clarified yet." (PMID 38172737, 2024). "Considering the results in the current study and previous findings together, we speculated that attenuation of exp‐CAF 544 cells' tumor‐promoting ability by RUNX3 knockdown is likely dependent on a signaling pathway(s) in which neither SDF‐1 nor TGF‐β is involved." (PMID 37641472, 2023). "Moreover, RUNX3 activity was predicted to repress multiple tumor types (left)." (PMID 37400551, 2023). "We propose that increased RUNX3 expression could contribute to the tumor‐promoting ability of CAFs." (PMID 37641472, 2023). "Clinical implications of loss of RUNX3 and/or SMAD4 expression in the tumor epithelial compartment may be used to identify stage II patients in need of adjuvant chemotherapy, or patients with T1-3N1 tumors eligible for extended chemotherapy compared to the three month standard for this risk group." (PMID 36900240, 2023). "Since Runx3 is also an important tumor suppressor gene, to demonstrate that the enhanced immune response we observed was due to T-cell-specific Runx3 function rather than an indirect result of tumor cells, we constructed mice with conditional knockout of Runx3 in T cells." (PMID 37189103, 2023).
tumor (continued). "RUNX3 is required to promote chromatin accessibility to genes encoding IRF4 and Blimp transcription factors for CD8+ memory T cells, so it will be of great interest to compare the epigenetic landscapes between CD8+ TCM and CD8+ TRM cells under various tumor settings." (PMID 36231078, 2022). "RUNX3 is expressed on various solid tumors and may contribute to tumor immunosuppression." (PMID 35522574, 2022). "Current studies have, overall, identified RUNX3 as the dominant member in controlling NK- and CD8+ CTL-mediated antitumor immune responses, but whether RUNX3 is also implicated in controlling the functions of tumor-associated ILCs and myeloid cells is obscure." (PMID 36231078, 2022). "In addition to Hobit and Blimp1, Runx3 was also reported to be critical in regulating T cell residency in the intestine, and its overexpression promoted T cell infiltration into the tumor microenvironment and control of tumor growth." (PMID 35985020, 2022). "This treatment could indeed upregulate RUNX3 expression, causing a decreased tumor growth, but other effects of resveratrol could not be excluded." (PMID 34639015, 2021). "Therefore, the methylation level of RUNX3 can also influence tumor cell phenotype." (PMID 33575207, 2020). "Therefore, RUNX3 represents a therapeutic target for diverse tumour types." (PMID 30535344, 2019). "Notably, we revealed that deletion of miR-301a leads to CD8+ T cell accumulation, IFN-γ production, and tumor metastatic suppression by elevating Runx3, suggesting that miR-301a is a key regulator of the tumor microenvironment in the initiation of tumorigenesis." (PMID 31122259, 2019). "To determine whether miR-301a deletion raises Runx3 expression in tumor-infiltrating immune cells, we isolated CD8+ T cells, CD4+ T cells, CD11b+ cells (including monocytes and macrophages), and CD11c+ cells (including dendritic cells), from B16 tumors developed in WT and miR-301a−/− mice." (PMID 31122259, 2019). "Moreover, knockdown of TOX was associated with increase in RUNX3 expression levels, indicating that TOX may act to decrease RUNX3′s tumor suppressor functions in SS." (PMID 31139323, 2019). "No significance was detected on survival time between RunxWT;Runx3WT;Nf1fl/fl;DhhCre and Runx1fl/+;Runx3fl/+;Nf1fl/fl;DhhCre mice, suggesting that loss of each allele of Runx1 and Runx3 only might not change tumor penetration rate." (PMID 31032403, 2019). "Indeed, Runx3 deficiency impaired TIL accumulation without affecting migration to the tumor, associated with an increase in tumor growth." (PMID 30158938, 2018). "Because EMT activation results in tumor cell migration and invasion, our group measured levels of the E-cadherin and vimentin, which are markers for epithelial and mesenchymal, in cells transfected with control or RUNX3 plasmids or control siRNA or RUNX3 siRNA." (PMID 29254144, 2017). "We found that RUNX3 staining was mainly situated in the cytoplasm and nucleus of cancer cells in matched non-tumor tissues, while RUNX3 staining level was decreased in cancer tissues compared with matched non-tumor tissues (P <0.001), indicating that RUNX3 was involved in the development of HCC." (PMID 28977878, 2017). "However, the role of RUNX3 as a tumor suppressor in the progression and prognosis of BC remains unclear due to the small sample size of individual studies." (PMID 27825140, 2017). "In addition, we for the first time demonstrated the inhibitory effect of baicalein on RUNX3, another tumor suppressor whose reduced expression may play an important role in the development and progression of several cancer types including lung." (PMID 25948105, 2015). "Conventional chemotherapy can induce resistance to chemotherapeutic agents, and tumor regrowth mediated by CSCs, therefore targeting RUNX3 gene and its related signaling pathways could be another mechanism for therapeutic approaches for cancer treatment aiming at CSC elimination." (PMID 25229459, 2014).
tumor (continued). "We speculated that this is due to the tumor angiogenesis inhibition induced by RUNX3." (PMID 24475196, 2014). "The lost of RUNX3 expression may contribute to the tumor invasion and growth." (PMID 23457532, 2013). "The data indicate that RUNX3 may be a tumor suppressor involved in the progression of RCC." (PMID 23457532, 2013). "However, little is known about the role of RUNX3 in HCC tumor suppression." (PMID 21205319, 2011). "RUNX3 plays a crucial role in TGF-β signaling via binding with Smad family including Smad2, Smad3 and Smad4 and tumor suppression pathways." (PMID 40354349, 2025). "In a hepatocellular carcinoma model, GPC3-BBz CAR-T cells with RUNX3 overexpression exhibited better tumor control, with increased CAR-T cell numbers in blood and tumor tissue, along with a higher proportion of Tem cells." (PMID 40693464, 2025). "These associations were particularly strong for cell cycle-/apoptosis-related genes (RUNX3, RASSF1A, and CDH13), suggesting that epigenetic silencing of key regulatory checkpoints facilitates early tumor recurrence and progression." (PMID 41377897, 2025). "RUNX3 has been shown to promote CDH1 expression and inhibit EMT and cell migration, thereby restraining tumor invasion and progression." (PMID 41002582, 2025). "Conversely, Runx3 overexpression increased the number of TRM cells, slowed tumor growth, and extended survival." (PMID 39802636, 2025). "Runx3, a central regulator for the development of CD8+TRM cells across various tissues, is also upregulated in tumor‐specific CD8+TRM cells." (PMID 40066223, 2025). "Conversely, elevated expression of Runx3 led to increased density of TIL in tumor tissue and improved tumor prognosis." (PMID 38426090, 2024). "Attention is shifted to RUNX3, another key member of the RUNX family, commonly acknowledged as a tumor suppressor, to explore its potential role in the regulation of angiogenesis." (PMID 38430423, 2024). "Exploiting RUNX3-driven transcriptional networks is thus an attractive strategy to enhance CAR-T cell therapy, as accumulation within the tumour bed is imperative for CD8+ T cell-mediated tumour control." (PMID 39399500, 2024). "The predictive value of the RUNX3 pathway signature was assessed for IO/TKI therapy, as well as its correlation with tumor microenvironment components, especially with CD8+ T cells." (PMID 38172737, 2024). "We demonstrate that increased expression of RUNX3 and SMAD4 in tumor epithelial and stromal compartments and IRS-1 in stroma are independent predictors of a favorable prognosis in this patient group." (PMID 36900240, 2023). "Among them, RUNX1 was relatively more highly expressed than the other two RUNX genes, and the significant difference in RUNX1 expression between tumor and para-tumor tissues excluded the role of RUNX2 and RUNX3, suggesting the importance of abundant RUNX1." (PMID 37697370, 2023). "Both RUNX3 and MIZ-1 genes reside within chromosome 1p36, a region which is frequently deleted in cancer and which has been postulated to contain several tumor suppressors that work together." (PMID 37400551, 2023). "As illustrated in the heat maps, a negatively significant correlation was noted between RUNXs expression and the tumor purity in several tumor types; specifically in 19 tumor types for RUNX1, in 21 types for RUNX2, and in 23 types for RUNX3." (PMID 36321611, 2023). "High expression of IRS1 in stromal tissue and RUNX3 and SMAD4 in both stromal and tumor tissue were positive prognostic factors." (PMID 36900240, 2023). "RUNX3 had the ability to form a ternary complex with beta-catenin/TCF4, leading to the suppression of Wnt signaling activity and the suppression of tumor." (PMID 38007527, 2023). "To further investigate the role of Runx3 in CD8 + T cells, we applied single-cell flow mass spectrometry analysis (CyTOF) and found that the proportion of CD8+ tumor infiltrating lymphocytes (TILs), changed significantly." (PMID 37189103, 2023).
tumor (continued). "Macrophage infiltration was recorded in 22 tumor types for RUNX1, in 25 types for RUNX2, and in 18 types for RUNX3." (PMID 36321611, 2023). "In addition, excessive expression of RUNX1 under certain experimental conditions may functionally mimic tumor-suppressive RUNX3 (as described later) depending on the similarity of the consensus sequence for DNA binding, suggesting the presence of functional redundancy." (PMID 36831211, 2023). "We further explored the relationship between the different RUNXs expression and the abundance of tumor-infiltrating lymphocytes (TILs) through TISIDB analysis and found that RUNX1, RUNX2, and RUNX3 were positively correlated with TILs." (PMID 36321611, 2023). "CD8+ T cell infiltration was recorded in 21 tumor types for RUNX1, in 18 types for RUNX2, and in 21 types for RUNX3." (PMID 36321611, 2023). "Stromal IRS-1 was moderately (0.4 < r < 0.6) correlated with tumor epithelial and stromal SMAD4, and tumor epithelial and stromal RUNX3, indicating a possible link between stromal IRS-1 and pathways involving activated SMAD4 and RUNX3." (PMID 36900240, 2023). "For example, the tumor suppressors p21 and ARF are induced at the R-point and then subsequently suppressed, with RUNX3 playing key roles in both programs." (PMID 36899846, 2023). "A significant positive correlation was noted between RUNXs expression and B cell infiltration in several tumor types; specifically, in 17 types for RUNX1, in 18 types for RUNX2, and in 21 types for RUNX3." (PMID 36321611, 2023). "We also investigated at the pan-cancer and inter-tumor heterogeneity of RUNX gene family expression, and found that RUNX1 and RUNX3 were highly expressed at the pan-cancer level, whereas RUNX2 was modestly expressed." (PMID 35522574, 2022). "Meanwhile, downregulation of Zeste Homolog 2 (EZH2) can reduce the methylation level of RUNX3, and silencing EZH2 can inhibit the re-methylation of tumor cells." (PMID 36476345, 2022). "The results revealed that the expression levels of RUNX1, RUNX2, RUNX3 were higher in tumor tissues than in normal tissues, especially the expression of RUNX2 and RUNX3." (PMID 36092942, 2022). "Thus, it may seem that RUNX3 acts differently in various malignancies and both an increase and reduction in gene expression level may contribute to the development and progression of neoplastic disease." (PMID 36005134, 2022). "Logistic regression analysis showed that high expression of RUNX3, low expression of EZH2, and clinical N (cN) stage were good predictors of tumor regression response and down-staging." (PMID 35280723, 2022). "In contrast, when tumor grade grew, RUNX1 expression in BLCA and BRCA declined, and RUNX3 expression in TGCT decreased." (PMID 35522574, 2022). "RUNX family transcription factor 3 (AML2) forms a heterodimeric complex core-binding factor (CBF) with CBFB and functions as a tumor suppressor." (PMID 34828279, 2021). "Positive regulation of CCL3 and CCL20 by RUNX3 contributes to the recruitment of CD8 T cells into the microenvironment of lung adenocarcinoma, supporting anti-tumor immunity." (PMID 34421907, 2021). "In particular, two genes, RUNX3 and CXCR6, have high positive correlation across six immune cell types and higher expressions in tumor samples than normal samples." (PMID 33919884, 2021). "The TOX-RUNX3 pathway inhibits the expression of RUNX3 when TOX is highly expressed, thereby affecting the tumor suppression function." (PMID 33743809, 2021). "For example, in response to EMT-mediating inflammatory cytokines, the transcription factor Runt-related Transcription Factor 3 (RUNX3) binds to the Forkhead Box P3 (FOXP3) promoter and increases the Treg population within the tumor." (PMID 34830776, 2021).